Y_RNA (Y RNA )
Gene: Miscellaneous RNA gene on chromosome 15 (49,137,762 to 49,137,863, reverse strand). Ensembl gene ENSG00000200120.
Homologues: Orthologues: chimpanzee Y_RNA (98% identical), macaque Y_RNA (96% identical). Paralogues in human: RNY3 (90% identical), Y_RNA (90% identical), Y_RNA (89% identical), RNY3P1 (88% identical), Y_RNA (88% identical), Y_RNA (87% identical), Y_RNA (86% identical), Y_RNA (85% identical), RNY3P11 (84% identical), Y_RNA (84% identical), Y_RNA (83% identical), Y_RNA (82% identical), and 97 more.